CNTNAP2 (contactin associated protein 2)
Description:
Required for gap junction formation (Probable). Required, with CNTNAP1, for radial and longitudinal organization of myelinated axons. Plays a role in the formation of functional distinct domains critical for saltatory conduction of nerve impulses in myelinated nerve fibers. Demarcates the juxtaparanodal region of the axo-glial junction.
Synonyms: CASPR2; KIAA0868; NRXN4; AUTS15; CDFE; PTHSL1
Tractability: Antibody: UniProt predicts a signal peptide or a membrane-spanning region. PROTAC: ubiquitination databases record sites on it; its protein half-life has been measured.
Gene: Protein-coding gene on chromosome 7 (146,116,002 to 148,420,998, forward strand). Ensembl gene ENSG00000174469.
Subcellular location: Membrane; Cell projection, axon; Cell junction, paranodal septate junction
Gene Ontology:
Molecular function: enzyme binding; protein binding; protease binding; transmembrane transporter binding
Biological process: adult behavior; cell population proliferation; cerebral cortex development; learning; limbic system development; positive regulation of gap junction assembly; social behavior; striatum development; superior temporal gyrus development; thalamus development; vocal learning; vocalization behavior; brain development; clustering of voltage-gated potassium channels; nervous system development; neuron projection development; neuron projection morphogenesis; neuron recognition; protein localization to juxtaparanode region of axon; signal transduction; transmission of nerve impulse; central nervous system development; prepulse inhibition; startle response
Cellular component: axolemma; cell surface; early endosome; Golgi apparatus; membrane; voltage-gated potassium channel complex; axon; dendrite; juxtaparanode region of axon; neuronal cell body; perikaryon; plasma membrane; synapse; GABA-ergic synapse; glutamatergic synapse; paranodal junction; paranode region of axon; presynaptic membrane; synaptic membrane
Genetic constraint (gnomAD): Loss-of-function variants: 98 observed, 160.66 expected, observed/expected ratio (o/e) 0.61, 90% interval 0.52 to 0.72. The upper end of that interval is the gene's LOEUF score, 0.72, which puts it in group 2 of 6, group 1 being the genes least tolerant of losing a copy. Missense variants: 1,725 observed, 1,755.6 expected, observed/expected ratio (o/e) 0.98, 90% interval 0.94 to 1.02. Synonymous variants: 651 observed, 659.62 expected, observed/expected ratio (o/e) 0.99, 90% interval 0.93 to 1.05.
Gene-disease validity (ClinGen):
ClinGen rates the evidence that CNTNAP2 causes each of these diseases.
complex neurodevelopmental disorder (autosomal recessive): Definitive. A disorder that involves more than one phenotype associated with the central nervous system, including but not limited to intellectual disability, autism, and seizures (epilepsy).
complex neurodevelopmental disorder (autosomal dominant): Disputed.
Homologues: Orthologues: chimpanzee CNTNAP2 (99% identical), macaque CNTNAP2 (99% identical), rabbit CNTNAP2 (96% identical), dog CNTNAP2 (95% identical), guinea pig CNTNAP2 (94% identical), mouse Cntnap2 (94% identical), rat Cntnap2 (94% identical), tropical clawed frog cntnap2 (76% identical), zebrafish cntnap2b (64% identical). Paralogues in human: CNTNAP5 (50% identical), CNTNAP4 (47% identical), CNTNAP3 (45% identical), CNTNAP3B (45% identical), CNTNAP1 (43% identical), NRXN2 (23% identical), NRXN3 (23% identical), NRXN1 (22% identical), CNTNAP3C (17% identical), CUBN (16% identical), F8 (14% identical), F5 (13% identical), and 23 more.
Diseases named in the same sentence as CNTNAP2 in open-access papers:
CNTNAP2 is named in the same sentence as 238 diseases in open-access papers, as found by Europe PMC text mining. Sharing a sentence is not in itself a finding about the gene and the disease. The quoted sentences say what the papers report.
autism (193 papers, 2009 to 2026). Persistent deficits in social interaction and communication and interaction as well as a markedly restricted repertoire of activity and interest as well as repetitive patterns of behavior. "Here, we show that CNTNAP2 knockout mice exhibit many of the behavioral features observed in patients with idiopathic autism and with recessive CNTNAP2 mutations that cause a syndromic form of autism." (PMID 40642208, 2025). "CNTNAP2 has previously been linked to autism and intellectual disability, BRAF to epilepsy, TRANK1 to schizophrenia, and LRPPRC/MYO7A to mitochondrial and ciliary disorders." (PMID 40282380, 2025). "Because CNTNAP2 is an autism risk gene, we compared this dataset to the SFARI (Simons Foundation Autism Research Initiative) autism gene database and confirmed 31 overlapping genes." (PMID 39758604, 2025). "CNTNAP2 is associated with various neurodevelopmental disorders, including schizophrenia, epilepsy, autism, attention-deficit hyperactivity disorder, and intellectual disabilities." (PMID 40826483, 2025). "Researchers have begun using meta-analysis methods to analyze metaphorical language data and genotyping technology to reveal the association between CNTNAP2 variants and autism." (PMID 39328816, 2024). "Taken together, these data demonstrate that the mutation of α-cleavage site in CNTNAP2 leads to autism-like repetitive and social behavior abnormalities, and restoring α-cleavage product C79 expression improves autism-like phenotypes." (PMID 38424048, 2024). "CNTNAP2 has been associated with neurological disorders such as epilepsy, intellectual disability, and autism, especially with language impairment." (PMID 38539661, 2024). "CASK is part of a signaling pathway that includes the widely validated autism susceptibility gene CNTNAP2 and the Prader Willi syndrome gene NECDIN." (PMID 38978588, 2024). "One candidate-autism gene is contact in associated protein 2 (CNTNAP2), and variants in this gene are associated with sensory deficits and anatomical differences." (PMID 39677787, 2024). "Deletion of the autism-associated Cntnap2 gene disrupts the density of PV + interneurons within the hippocampus, leading to imbalances in inhibitory neurotransmission in the perisomatic region." (PMID 39695746, 2024). "Variants in the autism-candidate gene contactin associated protein 2 (CNTNAP2) are associated with sensory deficits and anatomical differences." (PMID 39677787, 2024). "The matrix marker, Cntnap2, an autism susceptibility gene, with as large a compartmental difference in expression as Epha446, was upregulated in SPNs other than matrix SPNs (S-D1, O-D2 and S-D2)." (PMID 36650127, 2023). "As possible targets we chose long genes which are associated with autism, namely Nrxn1, Nlgn1, contactin-associated protein 2 (Cntnap2) and discs large MAGUK scaffold protein 2 (Dlg2)." (PMID 36768419, 2023). "Mutations in CNTNAP2, an autism susceptibility gene, also results in a reduction in GABAergic neurons as well as hyperactivity, and changes in behavior in mice and zebrafish." (PMID 37465584, 2023). "The Contactin-Associated Protein 2 (CNTNAP2) gene is involved in nervous system development and has been implicated in disorders such as autism and intellectual disability in association with exposure to MSP." (PMID 37628696, 2023). "Among the risk genes associated with autism, mutations in the contactin-associated protein-like 2 (CNTNAP2) gene leads to a syndromic form of ASD and cortical dysplasia focal epilepsy (CDFE)." (PMID 37371370, 2023). "Organoids with the CNTNAP2 mutation showed differential expression of autism-associated genes, such as CASK, ETFB, PBX1, and NR4A2, in excitatory neurons compared to excitatory neurons in control organoids." (PMID 37321420, 2023). "For example, deletion of the autism-risk gene contactin-associated protein 2 (Cntnap2) reduced the number of GABAergic interneurons in mouse cortex, including fast-spiking parvalbumin-immunopositive interneurons." (PMID 36768529, 2023).
autism (continued). "Homozygous loss-of-function mutations in CNTNAP2 cause a rare and severe neurodevelopmental syndrome that includes autism symptoms." (PMID 37321420, 2023). "Whereas it only remains a possibility, the presence of autism risk factor in the CNTNAP2 gene, signs for severe bruxism, and the distinctive burial treatment of individual S45 suggest the actual onset of symptoms." (PMID 37562011, 2023). "CNTNAP2 is a master gene that causes speech-language delay and is central to the manifestation of autism." (PMID 37069342, 2023). "Cntnap2-deficient mice also show core autism-relevant behaviors, including the social deficits and repetitive behavior." (PMID 37271769, 2023). "CNTNAP2, a protein associated with autism, helps to stabilize newly formed dendritic spines in the forebrain." (PMID 37691105, 2023). "The presence of autism-associated behavioral phenotypes in Cntnap knockout mice, such as hyperactivity and epileptic seizures, is an indication of the potential role of CNTNAP2 in the pathogenesis of psychiatric disorders." (PMID 36430976, 2022). "Recent work in in vitro cell culture models has shown that loss of one CNTNAP2 allele is sufficient to impact axonal growth and heterozygous missense variants identified in patients with autism were associated with deficits in protein trafficking." (PMID 35911904, 2022). "The CNTNAP2 protein is encoded by the CNTNAP2 gene, whose variability has been associated with mental retardation, autism, epilepsy, and schizophrenia." (PMID 36430976, 2022). "Pathogenic variants in PRICKLE2 are associated with myoclonic epilepsy and in CNTNAP2 are associated with autism and cortical dysplasia focal epilepsy syndrome." (PMID 34816733, 2021). "In this work, we investigated sensory processing in the cerebellum in vivo in the Cntnap2 mouse model of autism, an autism-linked gene involved in cerebellar development and function." (PMID 34593517, 2021). "Among identified human ASD risk genes, contactin-associated protein-like 2 (CNTNAP2), which encodes a synaptic cell adhesion molecule, is considered by the Simons Foundation Autism Research Initiative (SFARI) to be a strong ASD candidate." (PMID 34758298, 2021). "Perturbed gamma oscillations and sharp wave ripples (SWP-Rs) in area CA1 of Cntnap2 KO mice associated with impaired spatial discrimination highlight the involvement of the hippocampus in the autism phenotype." (PMID 34758298, 2021). "Further, autism-linked common genetic variation in CNTNAP2 has been associated with reduction in cerebellar gray matter volume, as determined by MRI." (PMID 34593517, 2021). "Mutations in the CNTNAP2 gene are partly responsible for autism and other disorders as the gene regulates neural connections in the frontal lobes." (PMID 34306007, 2021). "Contactin-associated protein-like 2 (CNTNAP2) is found to be strongly related to autism and epilepsy in consanguineous families." (PMID 34073947, 2021). "One autism-linked gene associated to cerebellar dysfunction both in humans and animal models is CNTNAP2." (PMID 34593517, 2021). "Loss of function mutations in the CNTNAP2 gene are associated with a syndromic form of autism that presents with cerebellar abnormalities, including hypoplasia of the cerebellar vermis and hemispheres." (PMID 34593517, 2021). "Another aspect supporting the role of CASPR2 autoantibodies in MAR autism is the association of loss of function Contactin Associated Protein 2 gene (CNTNAP2) mutations with rare genetic forms of autism." (PMID 32784803, 2020). "Alterations to the CNTNAP2 gene associated with autism include intragenic deletions, copy number variations (CNVs), and heterozygous missense variants located throughout the gene." (PMID 33262688, 2020). "Autism-related variants in CNTNAP2 have been shown to impair axonal growth of cortical neurons and reduced excitatory and inhibitory synaptic inputs on neurons of the prefrontal cortex." (PMID 33262688, 2020).
autism (continued). "Contactin associated protein-like 2 (CNTNAP2) is the first widely replicated autism-predisposition gene." (PMID 30816216, 2019). "In this study, a contactin-associated protein-like 2 (Cntnap2) mutant mouse model of autism was used." (PMID 31071949, 2019). "Other cognitive disorders, such as schizophrenia, epilepsy, autism, and attention-deficit hyperactivity disorder, were also linked to disruptions in CNTNAP2 gene (Rodenas-Cuadrado, Ho, & Vernes, 2014)." (PMID 31446765, 2019). "Associated SNPs and heterozygous deletions in CNTNAP2 were subsequently reported in autism, schizophrenia and other psychiatric or neurological disorders." (PMID 30586385, 2018). "During the last decade, several association studies have been performed to assess the role of common variants of CNTNAP2 in autism or speech-related phenotypes, as well as several other psychiatric phenotypes." (PMID 30586385, 2018). "The neurexin family membrane protein CNTNAP2 is a target of FoxP2, and has been linked to language disorders as well as autism." (PMID 29920554, 2018). "Contactin-associated protein 2 (Cntnap2), which encodes a cell-adhesion molecule of the neurexin family, is an important autism-associated gene identified in previous studies." (PMID 28966979, 2017). "A number of studies have found that contactin-associated protein 2 (Cntnap2) knockout (KO) mice, a well-established mouse model of autism, exhibit reduced interneuron numbers and aberrant phasic inhibition." (PMID 28966979, 2017). "Mutational screening of CNTNAP2, which is classified as a strong autism risk gene, uncovered a novel CNTNAP2 5 bp intronic insertion upstream of exon 23 in Lebanese ASD cases and unaffected controls." (PMID 28358038, 2017). "We revealed that not only phasic inhibition but also tonic inhibitory transmission was reduced in a developmental-dependent fashion in a mouse model with deletion of the autism-risk gene, contactin-associated protein 2 (Cntnap2)." (PMID 28966979, 2017). "Mutations in the gene encoding CASPR2, CNTNAP2, are associated with schizophrenia, epilepsy and autism." (PMID 26667479, 2016). "Common polymorphisms in CNTNAP2 have been associated with language delay in autism and the general population; and more specifically to phonological memory and reading abilities in language impairment." (PMID 27064276, 2016). "Heterozygous mutations in CNTNAP2 have been identified in patients with a range of complex phenotypes including intellectual disability, autism and schizophrenia." (PMID 26843181, 2016). "The current knowledge regarding the potential link between ASDs and ER stress is minimal and mainly based on autism-associated mutations in CNTNAP2 and the synaptic adhesion protein CADM1." (PMID 26621873, 2016). "The findings are reminiscent of those seen in autistic spectrum disorders, and mutations/polymorphisms in the CASPR2-encoding gene, CNTNAP2, have been linked to autism." (PMID 25491076, 2015). "The second mouse model harbors homozygous null mutations in Cntnap2, associated with autism and Pitt-Hopkins-like syndrome." (PMID 26273832, 2015). "In non-ASD individuals, those who are homozygous for an allele on the autism candidate gene CNTNAP2 show significantly reduced GM in the cerebellum in bilateral Crus I." (PMID 26045942, 2015). "The CNTNAP2 gene has been implicated in a broad range of phenotypes, including autism, Pitt-Hopkins-like mental retardation, schizophrenia, dyslexia and language impairment, delayed motor development, and mild ataxia." (PMID 25648254, 2015). "Implicated in autoimmune encephalitis, neuromyotonia and genetic forms of autism, here we report that contactin-associated protein-like 2 (CNTNAP2) contains a potential autoepitope within the extracellular region." (PMID 24466509, 2014). "CNTNAP2, or contactin associated protein-like 2, is one of the genes with the strongest evidence of autism susceptibility with convergent evidence from several independent studies." (PMID 24147096, 2013).
autism (continued). "Although we have demonstrated dysregulation of CNTNAP2 gene expression, it appears that common variants in CNTNAP2 have a limited role in autism susceptibility." (PMID 24147096, 2013). "Using a logistic expression analysis, we observed that altered CNTNAP2 expression is highly associated with autism status (p = 1.9 x 10-5)." (PMID 24147096, 2013). "Using a logistic expression analysis we observed that altered CNTNAP2 expression is highly associated with autism status (p = 1.9 x10-5), with both high and low expression observed in cases, though low levels were more prevalent." (PMID 24147096, 2013). "Rare variants of the contactin-associated protein-like 2 (CNTNAP2) gene can increase the risk of developing autism." (PMID 24151553, 2013). "It remains entirely possible that CNTNAP2 harbors a diversity of coding and non-coding mutations that will be important for understanding autism and ASD pathophysiology, but its epidemiological impact is small." (PMID 24147096, 2013). "Recently, Dennis and colleagues provided whole-brain measures for the association of structural network structure and the presence of rs2710102 CNTNAP2 autism risk gene." (PMID 23593367, 2013). "CNTNAP2, as well as other autism-associated genes, show defects in the normal development of connectivity." (PMID 22937139, 2012). "We propose that these CNTNAP2 variants increase susceptibility to SLI or autism when they occur together with other risk factors." (PMID 21310003, 2011). "The SNP rs7794745 located within CNTNAP2 has a high RI in both sexes whereas a previous association with autism has been reported preferentially in males." (PMID 22017886, 2011). "In earlier work, based on low-throughput shotgun sequencing of human FOXP2-ChIP fragments, we identified a FOXP2-bound element in the first intron of CNTNAP2 (contactin-associated-protein-like-2) a gene implicated in language impairments and autism." (PMID 21765815, 2011). "It is believed that FOXP1interacts with FOXP2 and CNTNAP2, both implicated in speech disorders and autism." (PMID 22102821, 2011). "CNTNAP2 is also associated with autism and significantly correlated with NWR test scores in children with SLI." (PMID 20345892, 2010). "Linkage, association, and gene-expression analyses identify CNTNAP2 as an autism-susceptibility gene." (PMID 21034472, 2010). "It is worth mentioning here that FOXP2 protein dramatically down-regulates CNTNAP2, a strong candidate gene for autism, whereas OXT gene encodes the neuropeptide binding the oxytocin receptor (OXTR), another strong candidate gene for autism." (PMID 20885821, 2010). "For instance, variable dosage of CNTNAP2 has also been documented in epilepsy and schizophrenia, while deletion of 15q13.3 has been implicated in autism, generalized learning disability, epilepsy, and schizophrenia." (PMID 20346443, 2010). "CNTNAP2 gene variations are correlated with increased risk of autism." (PMID 40642208, 2025). "CNTNAP2 was curated by ClinGen in 2019 (HI score of 1), highlighting its emerging association with autosomal dominant complex neurodevelopmental disorders, including ID, DD, epilepsy, schizophrenia, Tourette syndrome, and increased susceptibility to autism." (PMID 40869922, 2025). "Shank3 and Cntnap2 are autism-associated genes with distinct roles in neurons." (PMID 41062277, 2025). "Interestingly, the genes contributing to the suppressed pathways that regulate the development of the central nervous system included SHANK2 and CNTNAP2, deletions of which are associated with autism and intellectual disability." (PMID 36084040, 2023). "Common genetic variants of CNTNAP2 are associated with increased susceptibility to autism." (PMID 37371370, 2023). "Autism is associated with gene mutations such as Cntnap2 (the gene encoding contact associated protein like protein 2), intraperitoneal or intranasal injection of oxytocin can improve the social behavior defects of Cntnap2 gene ineffective mutant mice." (PMID 35937893, 2022).